NAP1L4 (nucleosome assembly protein 1 like 4)
Description:
Acts as a histone chaperone in nucleosome assembly.
Synonyms: NAP2; NAP1L4b; NAP2L; hNAP2
Tractability: PROTAC: ubiquitination databases record sites on it; its protein half-life has been measured.
Gene: Protein-coding gene on chromosome 11 (2,944,429 to 2,992,386, reverse strand). Ensembl gene ENSG00000205531.
Subcellular location: Nucleus; Chromosome; Cytoplasm
Subcellular location (Human Protein Atlas): Nucleoplasm
Gene Ontology:
Molecular function: nucleosome binding; protein binding; RNA binding
Biological process: nucleosome assembly
Cellular component: cytoplasm; nucleoplasm; nucleus; chromatin; chromosome; dendrite; neuronal cell body
Genetic constraint (gnomAD): Loss-of-function variants: 13 observed, 53.67 expected, observed/expected ratio (o/e) 0.24, 90% interval 0.16 to 0.38. The upper end of that interval is the gene's LOEUF score, 0.38, which puts it in group 1 of 6, group 1 being the genes least tolerant of losing a copy. Missense variants: 368 observed, 456.74 expected, observed/expected ratio (o/e) 0.81, 90% interval 0.74 to 0.88. Synonymous variants: 168 observed, 159.14 expected, observed/expected ratio (o/e) 1.06, 90% interval 0.93 to 1.2.
Homologues: Orthologues: chimpanzee NAP1L4 (99% identical), macaque NAP1L4 (98% identical), guinea pig NAP1L4 (96% identical), dog NAP1L4 (95% identical), mouse Nap1l4 (94% identical), rat Nap1l4 (94% identical), pig NAP1L4 (93% identical), rabbit NAP1L4 (89% identical), tropical clawed frog nap1l4 (75% identical), zebrafish nap1l4b (66% identical). Paralogues in human: NAP1L1 (66% identical), NAP1L2 (42% identical), NAP1L3 (35% identical), SET (25% identical), SETSIP (23% identical), TSPYL2 (18% identical), TSPYL4 (16% identical), TSPYL1 (15% identical), TSPYL5 (14% identical), NAP1L5 (14% identical), TSPYL6 (13% identical), TSPY1 (13% identical), and 6 more.
Diseases named in the same sentence as NAP1L4 in open-access papers:
NAP1L4 is named in the same sentence as 9 diseases in open-access papers, as found by Europe PMC text mining. Sharing a sentence is not in itself a finding about the gene and the disease. The quoted sentences say what the papers report.
acute myeloid leukemia (1 paper, 2025). Acute myeloid leukemia (AML) is a group of neoplasms arising from precursor cells committed to the myeloid cell-line differentiation. "Mutations, deletions, and aberrant expressions of Nap1L4 are observed in diseases such as acute myeloid leukemia (AML)." (PMID 41387107, 2025).
major depression (1 paper, 2021). "There were several suggestive hits for cyclothymic temperament at the gene level as well, including NAP1L4 where a functional effect was also observed and which has been mentioned at a suggestive significance level in association with major depression in a transcriptome-wide analysis." (PMID 34075027, 2021).
mental disorder (1 paper, 2023). A disease that has its basis in the disruption of mental process. "Other candidate genes, including ADCYAP1R1, NAP1L4, and ERBB4, have been reported in mental disorders." (PMID 37491364, 2023).
NAP1L4 also shares sentences with these, for which no sentence is quoted: cancer (2 papers); tumor (2); alcohol dependence (1); autism (1); schizophrenia (1); small-intestinal carcinoids (1).